CLDN17 (claudin 17)
Description:
Channel-forming tight junction protein with selectivity for anions, including chloride and hydrogencarbonate, and for solutes smaller than 9 Angstrom in diameter. In the kidney proximal tubule, may be involved in paracellular reabsorption of filtered anions. Does not affect water permeability.
Synonyms: MGC126552; MGC126554
Tractability: Antibody: UniProt places it where antibodies can reach, with high confidence; its Gene Ontology location is reachable by antibodies, with high confidence; UniProt predicts a signal peptide or a membrane-spanning region.
Gene: Protein-coding gene on chromosome 21 (30,165,565 to 30,166,805, reverse strand). Ensembl gene ENSG00000156282.
Subcellular location: Cell junction, tight junction; Basolateral cell membrane
Pathways (Reactome):
Cell-Cell communication: Tight junction interactions
Gene Ontology:
Molecular function: channel activity; paracellular tight junction channel activity; protein binding; identical protein binding; structural molecule activity
Biological process: paracellular transport; calcium-independent cell-cell adhesion; transmembrane transport
Cellular component: basolateral plasma membrane; plasma membrane; tight junction; bicellular tight junction; membrane
Genetic constraint (gnomAD): Loss-of-function variants: 3 observed, 1.47 expected, observed/expected ratio (o/e) 2.04. That is too few expected variants to judge how well the gene tolerates losing a copy. Missense variants: 294 observed, 291.45 expected, observed/expected ratio (o/e) 1.01, 90% interval 0.92 to 1.11. Synonymous variants: 134 observed, 113.87 expected, observed/expected ratio (o/e) 1.18, 90% interval 1.02 to 1.36.
Homologues: Orthologues: chimpanzee CLDN17 (98% identical), dog CLDN17 (91% identical), pig CLDN17 (86% identical), guinea pig CLDN17 (85% identical), rabbit CLDN17 (83% identical), mouse Cldn17 (82% identical). Paralogues in human: CLDN8 (56% identical), CLDN3 (45% identical), CLDN9 (45% identical), CLDN6 (44% identical), CLDN4 (42% identical), CLDN14 (39% identical), CLDN5 (38% identical), CLDN19 (37% identical), CLDN7 (36% identical), CLDN1 (35% identical), CLDN2 (34% identical), CLDN20 (31% identical), and 10 more.
Diseases named in the same sentence as CLDN17 in open-access papers:
CLDN17 is named in the same sentence as 24 diseases in open-access papers, as found by Europe PMC text mining. Sharing a sentence is not in itself a finding about the gene and the disease. The quoted sentences say what the papers report.
gastric cancer (2 papers, 2013 to 2018). A primary or metastatic malignant neoplasm involving the stomach. "In this respect, the loss of the claudin-10 and claudin-17 may resemble E-cadherin and together with this molecule, might contribute to the loose cell cohesion in gastric cancer." (PMID 24325792, 2013). "Positive expression of claudin-17 protein was found in 18.0% (9/50) of gastric cancer tissues and in 70.0% (35/70) of adjacent tissues." (PMID 24325792, 2013). "The expression rate of claudin-17 in gastric cancer tissues was lower than the rate in adjacent tissues (The Chi-square test/Chi-Square Goodness-of-Fit Test, P < 0.01)." (PMID 24325792, 2013). "Our study reveals that the expression of E-cadherin, claudin-10, and claudin-17 were down-regulated in gastric cancer tissue while the expression of claudin-14 was up-regulated and correlation between claudins and E-cadherin expression with lymphatic metastasis were observed." (PMID 24325792, 2013). "In addition, claudin-10, claudin-17 and E-cadherin were concurrently expressed in gastric cancer." (PMID 24325792, 2013). "The present work infers that the expression altered of claudin-10, claudin-14, claudin-17 and E-cadherin between human gastric cancers and adjacent non-neoplastic tissues correlate with lymph node metastasis." (PMID 24325792, 2013). "The positive expression rates of claudin-17 in gastric cancer tissues and adjacent non-neoplastic tissues were 18% and 70% (P < 0.01)." (PMID 24325792, 2013).
hepatocellular carcinoma (2 papers, 2018 to 2021). A malignant tumor that arises from hepatocytes. "Additionally, elevated tight junction proteins claudin-9 and claudin-17 stimulate migration and invasion of hepatocellular carcinoma (HCC) (liver cancer) cells through activation of the TYK2/STAT3 pathway." (PMID 34439323, 2021).
kidney injury (2 papers, 2022 to 2025). Trauma to the kidney. "We reported that Cldn17 contributes to electrolyte homeostasis and protection against oxidative stress, as evidenced by our findings from Cldn17−/− mice demonstrating kidney injury and increased reactive oxygen species, underscoring its role in renal physiology." (PMID 40332125, 2025).
acute kidney injury (1 paper, 2025). Sudden and sustained deterioration of the kidney function characterized by decreased glomerular filtration rate, increased serum creatinine or oliguria. "However, the Cldn17−/− mouse kidneys revealed acute kidney injury (AKI) without significant kidney edema, a finding further confirmed in the current study, as no Evan’s blue dye extravasation was observed in the kidneys as compared with the lungs and skin." (PMID 40332125, 2025).
bronchopulmonary dysplasia (1 paper, 2022). Bronchopulmonary dysplasia is a chronic respiratory disease that results from complications related to lung injury during the treatment of infant acute respiratory distress syndrome in low-birth-weight premature infants or from abnormal lung development in older infants. "This coincides with a clinical study linking altered CLDN17 expression to adhesion and diapedesis of agranulocytes and granulocytes, leading to bronchopulmonary dysplasia, a chronic lung disease." (PMID 35681477, 2022).
Cirrhosis (1 paper, 2018). A chronic disorder of the liver in which liver tissue becomes scarred and is partially replaced by regenerative nodules and fibrotic tissue resulting in loss of liver function. "High expression of CLDN17 was observed in 53.8% (28/52) of HCC tissues 30.0% (3/10) of non-neoplastic cirrhosis tissues, 40.0% (4/10) of histologically non-neoplastic tissues adjacent to the tumor and in 40.0% (12/30) of hepatic tissues (P = 0.0001 < 0.001)." (PMID 30219077, 2018). "CLDN17 expression was explored in 52 HCC tissues, 10 histologically non-neoplastic cirrhosis tissues, 10 histologically non-neoplastic tissues adjacent to the tumor and 30 histologically non-neoplastic hepatic tissues." (PMID 30219077, 2018).
head and neck cancer (1 paper, 2024). A primary or metastatic malignant neoplasm affecting the head and neck. "Another in vitro study investigated the role of CLDN17 in head and neck cancer cells, where CLDN17 gene expression profiles in oral cancer tissues were analyzed." (PMID 38731853, 2024).
kidney damage (1 paper, 2022). "Further, deficiency of Cldn17 in mice leads to negative effects, including but not limited to inflammation and kidney damage." (PMID 35681477, 2022).
kidney failure (1 paper, 2025). An acute or chronic condition that is characterized by the inability of the kidneys to adequately filter the blood. "While we have identified promising potential modifier variants in NFU1, DMD, HPS5, CLDN8 and CLDN17, their functional impact on FHHNC progression towards kidney failure remains to be characterized." (PMID 40173198, 2025).
leukocytosis (1 paper, 2025). "The direct link between Cldn17 deficiency in the mice’s lungs and inflammation is also supported by our observations of increased granulocytes and lymphocytes in the Cldn17−/− mouse blood compared with the Cldn17+/+ mice, indicating a state of leukocytosis." (PMID 40332125, 2025). "Monocytes exhibited an increasing trend, while granulocytes and lymphocytes were significantly elevated in the Cldn17−/− mice, indicating leukocytosis in the knockout group." (PMID 40332125, 2025).
oral cancer (1 paper, 2024). "Therefore, CLDN17 was proposed to have a tumor suppressor effect in oral cancer by inhibiting epithelial–mesenchymal transformation, tumor invasion, and migration." (PMID 38731853, 2024).
oral lichen planus (1 paper, 2022). Oral lichen planus is a chronic inflammatory oral condition of unknown aetiology characterized by T-cell-mediated chronic immune response and abnormal epithelial keratinization cycle. "Another clinical study reported a significant upregulation of CLDN17 in the biopsy samples from oral lichen planus, a chronic, T cell-mediated inflammatory, autoimmune mucosal disease, thus suggesting a potential role for CLDN17 in inflammation." (PMID 35681477, 2022).
rheumatoid arthritis (1 paper, 2025). A chronic, systemic autoimmune disorder characterized by inflammation in the synovial membranes and articular surfaces. "Moreover, genes associated with PPAR signaling and rheumatoid arthritis, such as Fabp4 and Ccl2, were also dysregulated, further supporting CLDN17’s role in immune homeostasis and metabolic pathways." (PMID 40332125, 2025).
cancer (3 papers, 2020 to 2022). A tumor composed of atypical neoplastic, often pleomorphic cells that invade other tissues. "CLDN17 overexpression is strongly linked to cancer metastasis and survival rate in patients with hepatocellular carcinoma and promotes cell migration and invasion in the hepatocyte line HL7702." (PMID 36620607, 2022). "As of today, the precise role of CLDN17 in physiology and pathology is unknown, except for some cancer cells in vitro." (PMID 35681477, 2022). "Until today, the role of Cldn17 in physiology and pathology in vivo has not been investigated, except for a few conflicting reports on its deficiency linking to several cancers." (PMID 35681477, 2022). "More research is needed to determine how CLDN17 contributes to the pathogenesis of cancer." (PMID 36620607, 2022).
tumor (2 papers, 2018 to 2024). "There was an association of lower CLDN17 expression with higher tumor staging, poorer tumor histological grading, and worse clinical prognosis." (PMID 38731853, 2024).
CLDN17 also shares sentences with these, for which no sentence is quoted: Alzheimer disease (1 paper); amyotrophic lateral sclerosis type 1 (1); breast carcinoma (1); chronic lung disease (1); frontotemporal dementia (1); Lung Injury (1); pancreatic cancer (1); Polydipsia (1); Thrombocytopenia (1).